BCL2 (BCL2 apoptosis regulator)
Diseases named in the same sentence as BCL2 in open-access papers (continued):
Sharing a sentence is not in itself a finding about the gene and the disease.
cancer (continued). "Cancer cells employ various strategies to avoid apoptosis, including the overexpression of anti-apoptotic proteins such as members of the Bcl-2 family and HK, and VDAC1 binds HK, Bcl-2, and Bcl-xL." (PMID 39334905, 2024). "In order to investigate the anti-cancer effect of HCFs on HepG2 and HC cells in addition to gene expression studies, the expression levels of BAX and BCL-2 proteins were also measured and BAX / BCL-2 ratio was determined." (PMID 38372909, 2024). "They showed that the simultaneous combination of cancer cells with cobalt ferrite nanoparticles and magnetic field exposure significantly improves the cytotoxic effect and also increases Bax gene expression and decreases HSP70 and Bcl2 genes." (PMID 39144409, 2024). "Furthermore, survivin, Bcl-2, cyclin D1, and VEGF were also found to be transcriptionally activated leading to enhanced cell survival, angiogenesis, and cancer progression." (PMID 38719798, 2024). "In addition, Bax -248G>A and Bcl-2 -938C>A SNPs have no direct association with overall cancer susceptibility nevertheless the relationship might have established ethnic specificity, and might be associated with increasing adverse prognosis of some cancers." (PMID 39205918, 2024). "In addition, NS5A proteins have the ability to obstruct the action of proapoptotic proteins, like caspase-3, Bcl-2, and necrosis factor alpha (TNF-α), which are essential for anti-cancer protection." (PMID 38898936, 2024). "Bcl-2, Survivin, IAP-1, Cyclin D1, and COX-2 are some of the key proteins involved in opposing apoptosis, relaying survival signals, driving the cell cycle, and promoting inflammation in cancer cells." (PMID 37835375, 2023). "Previous studies have shown that amygdalin (Amy) possesses anticancer activities against several cancer cell lines; we suggested that these compounds might disrupt AMPK/mTOR and BCL-2." (PMID 37726740, 2023). "Reducing the expression of Bcl-2 and GCR might be one of the ways cancer cells create a favorable environment for growth." (PMID 37370761, 2023). "For example, antiapoptotic proteins, such as BCL-2, BCL2L2 and MCL1, can block autophagy in cancer." (PMID 36768482, 2023). "Mechanistic anti-cancer assays were performed on Compound 2, revealing noteworthy changes such as MMP reduction, increase in ROS production, inhibition of anti-apoptotic protein BCL-2, and activation of BAX and caspase-3." (PMID 38188932, 2023). "The findings suggest that ARTS mimetics or activators might serve as potential therapeutic agents for cancers with high levels of XIAP, BCL-2, or BCL-XL." (PMID 36565718, 2023). "PTRH2 could affect key cellular processes involving cell reproduction and differentiation in response to adhesion by modulating the expression of Bcl2, PI3K/AKT, and ERK signaling pathways, which could promote cancer progression and metastasis." (PMID 37770477, 2023). "Similar to BCL-2, MCL-1 is highly expressed in a range of cancer cells." (PMID 37864894, 2023). "Unlike cancer cells, the normal Vero cells showed insignificant changes in caspase 3 activity and expression of Bax and Bcl2 genes." (PMID 36851428, 2023). "The survival of many cancer cells is safeguarded not by a single pro-survival BCL-2 protein but rather by two or even more of these proteins." (PMID 36342579, 2023). "While known driver mutations in MYB and the activation of Notch are not actionable targets right now, we have identified the BCL2 gene overexpression solely in LGACC cancer cells that has small molecular inhibitors including Gossypol and Disarib." (PMID 37370820, 2023). "We performed several necropsies, but Bcl2-Tg/Tfl-/- mice showed no other malignant tumor except for lymphadenopathy (data not shown)." (PMID 37304286, 2023).
cancer (continued). "In cancer cells, both BIM and BMF are frequently bound by BCL-2 anti-apoptotic proteins." (PMID 37761989, 2023). "In human cancer cells, the downregulation of pro-apoptotic proteins (e.g. Bax, Bak, Bad, Bim) and the upregulation of anti-apoptotic proteins (e.g. BCL-2, BCL-xl, MCL-1), inhibits the release of cytochrome c from mitochondria, leads to the immortal character of the cancer cells." (PMID 37730790, 2023). "Changes in the mRNAexpression of genes involved in the intrinsic process of apoptosis(Bcl-2, Bax, CASPASE-3, and CASPASE-9) in HepG2 cancer cells were examined by quantitative polymerasechain reaction (qPCR) using SYBR Green Master Mix to determine theeffects of CCM CD-decorated chitosan NP." (PMID 37744806, 2023). "In addition, BCL-2 and BCL- xL overexpression contributes to cancer in many solid tumors of the brain, breast, lung, and glioma cancers." (PMID 36795726, 2023). "Compounds that impinge on this mechanism, i.e. Bcl‐2 antagonists or BH3 mimetics, may prove to have useful anti‐cancer properties." (PMID 36369656, 2023). "Based on these findings, we reasoned that combination therapy targeting Bcl-2 and YAP might effectively reduce cancer stemness." (PMID 37730636, 2023). "Furthermore, in silico study revealed that plumbagin can bind to cancer signaling proteins, namely PI3Kγ, AKT1/PKBα, Bcl-2, NF-κB, and Stat3, which play a key role in the pathogenesis of cancer." (PMID 37110873, 2023). "Moreover, a novel BH3 mimetic named ABT-263 with high affinity for BCL-XL, BCL-2 and BCL-w has been proven to exert both cytotoxic and cytostatic effects on EC cells in vitro and has entered clinical trials for the treatment of cancer." (PMID 37564206, 2023). "Surprisingly, although venetoclax is a BCL2 inhibitor, an anti-apoptotic protein that is pathologically overexpressed and crucial to the survival of certain cancer cells, Caco-2 cell proliferation was not affected by treatment with this drug." (PMID 37275957, 2023). "Finally, we discuss the development of inhibitors of pro-survival BCL-2 proteins, termed BH3-mimetic drugs, as novel agents for cancer therapy." (PMID 36342579, 2023). "Our main approach was to design new small molecules as BCL-2 inhibitors with potential anti-cancer activity based on literature review and SAR studies, novel benzothiazole-based compounds were designed, synthesized and evaluated for their in vitro BCL-2 inhibitory activity." (PMID 37730790, 2023). "In addition, flavonoids can exert an effect on the expression, as well as on the activity of apoptotic proteins such as BCL-2, BAX, and cleaved caspase-3 (CASP3), which ultimately leads to the induction of apoptosis in cancer cells." (PMID 37446564, 2023). "Further, to evaluate the mechanism of cancer cell death via checking the gene expression, HGRCm ZnO NPs upregulated the BAX and Caspase 3 and 9 expression levels but downregulated Bcl-2 expression, indicating that the nanoformulation induced mitochondrial-mediated apoptosis." (PMID 36677964, 2023). "Apart from these CDK1 substrates, BCL2 apoptosis regulator (BCL2), BCL2 apoptosis regulator like 1 (BCL2L1), and dynamin 1 Like (DRP1) are phosphorylated by CDK1, mediating mitochondrial fusion and apoptosis in human cancer cells." (PMID 37311884, 2023). "Resistance mechanisms against CTLs, as well as increased expression of survival proteins [e.g., B-cell lymphoma 2 protein (BCL-2)] and tyrosine kinase receptors overexpression [e.g., human epidermal growth factor receptor 2 (HER2/neu)] can be developed by cancer cells." (PMID 37427115, 2023). "Moreover, we also detected several biomarkers of cancer proliferation and cell apoptosis such as VEGFA, EGFR and HIF-α, and the anti-apoptotic factor Bcl-2." (PMID 36855119, 2023).
cancer (continued). "Additionally, wogonin inhibits the cell cycle of cancer cell lines by inhibiting the expression of cyclin D1, cyclin B1, and CDK1, inducing apoptosis, improving the Bax/Bcl‐2 ratio, and increasing caspase‐3 cleavage." (PMID 37132286, 2023). "To investigate the potential mechanisms underlying the decrease in cytotoxicity of oxidative stress caused by Nrf3, we initially examined several cell signals (Akt, Bcl-2, p38, and JNK) that have been reported to play a significant role in oxidative stress in cancer." (PMID 38027228, 2023). "In particular, CDK6 was chosen for the function “pathway in cancer”, ADAM12 for the function “signaling by EGFR”, HDAC4 was selected for the function “regulation of cell differentiation”, and finally Bcl2 for the function “negative regulation of apoptotic processing”." (PMID 36498866, 2022). "Upregulation of BCL-2 and other antiapoptotic BCL-2 family members such as MCL-1 or BCL-XL help cancer cells evade apoptosis by binding proapoptotic sensitisers and activators and may contribute to drug resistance." (PMID 35295611, 2022). "Some results obtained in cancer tissues originating from the digestive system suggest that G6PD can counteract the programmed cellular death, as demonstrated by the lower expression of apoptotic markers Bcl-2 and Bcl-xL." (PMID 35565779, 2022). "Inhibitors of Bcl-2 and Mcl-1 can increase the frequency of DiM of normal fibroblasts (but not of cancer cells) but duration of mitotic arrest does not change in these cases." (PMID 36188556, 2022). "The non-pump resistance, in the case of cancer, indicates the activation of the cell anti-apoptotic protein (Bcl-2) defense pathway, which decreases the drug sensitivity." (PMID 36005484, 2022). "BCL-2, BCL2L1, BAD, and BAX may also be involved in the molecular mechanisms linking periodontal disease with cancer." (PMID 35804353, 2022). "The impact of OxA treatment on chemoresistant tumors, on the expression of various proteins such as Nrf2, p-eIF2α, ATF4, PolQ, FoxM1, and Bcl2, which are involved in cancer chemoresistance, is not shown." (PMID 35747788, 2022). "Given its multifunctional and dynamic roles in tumorigenesis, it is not surprising that Bcl-2 has been a popular target in cancer drug design." (PMID 35056993, 2022). "Inhibition of Bcl-2 and Bcl-xL increases Akt/PI3K inhibition-induced apoptosis in cancer cells." (PMID 35402265, 2022). "In addition, we also evaluated the protein levels of Bax, Bcl‐2, C-Caspase-3 and C-PARP, which are typical apoptotic proteins in cancer cells." (PMID 35690609, 2022). "Thus, we further determined the effect of HA-mExo-miR204 on the expression of BCL2 and RAB22A in these cancer cells." (PMID 36231028, 2022). "Notably, apoptosis is accompanied by the alternation of Bcl-2/Bax expression and MAPK signaling activation in several cancer cells." (PMID 35164001, 2022). "In cancer cells, the antiapoptotic protein Bcl-2 is not capable of forming heterodimeric complexes with the proapoptotic protein Bax, resulting in high Bax levels." (PMID 36364001, 2022). "Disrupting this complex regulation of IP3Rs by Bcl-2 and using IP3R-derived peptides could overcome apoptosis avoidance, one of the hallmarks of cancer, and is, thus, of core interest for the development of novel anti-cancer strategies." (PMID 36045908, 2022). "Noteworthy, in both murine and human PC cells, IL30 stands out as an upstream regulator of key drivers of inflammation, immunity and cancer, such as NFKB1 and BCL2, which in human PC cells can be efficiently suppressed by CRISPR/Cas9-mediated IL30 gene deletion." (PMID 36224639, 2022). "In general, magnolol significantly decreased Bcl-2 expression and increased Bax expression, leading to an upregulation of the Bax/Bcl-2 ratio; it also induced the release of cytochrome c, increased PARP cleavage, and consequently induced apoptosis in cancer cells." (PMID 36234977, 2022).
cancer (continued). "In pancreatic most cancers cells, in vivo apoptosis was brought about by luteolin through the suppression of the K-ras/GSK-3β/NF-κB pathway with the release of cytochrome C, caspase-3activation, and decline in Bcl-2/Bax ratio." (PMID 36247004, 2022). "Using qPCR assay for known genes modulated NT157 in other cancer models, we identified that NT157 decreased expression of oncogenes BCL2, CCND1, MYB, and MYC and increased genes related to cellular stress and apoptosis, JUN, BBC3, CDKN1A, CDKN1B, FOS, and EGR1 (all p < 0.05)." (PMID 36224313, 2022). "Carvacrol decreased cancer cells proliferation and apoptosis via decreasing matrix metalloprotease (MMP‐2, MMP‐9) expressions while downregulating the Bcl‐2 expression and inducing phosphorylation of extracellular regulated protein kinase and protein kinase B(p‐Akt) at the molecular level." (PMID 36348778, 2022). "Although there are some reports that the DNA methylation signature regulates apoptosis in cancer cells, no studies have shown a link between apoptosis-related genes such as BCL-2 or MCL-1, and DNA methylation." (PMID 35185150, 2022). "The top-performing drug models include targeted therapies against well-known cancer targets such as ERBBs, HDAC, BCL2, JAKs, PARP, ERK, CDKs, etc., and Lapatinib, Vincristine, and CAY10603 presented the best performing models with an average AUROC more than 0.9." (PMID 35618721, 2022). "EIF4A1 has been reported to directly determine the selective translation of oncoproteins, such as myc, myb, notch, cdk6, bcl-2 and ROCK1, which are critical regulators contributing to cancer survival, proliferation, migration, invasion, metastasis and chemoresistance." (PMID 36101357, 2022). "Because the rise of Bcl-2 expression in cancer cells is not accompanied by an increase in Cas-3 protein, Bcl-2 acts as an anti-apoptotic protein." (PMID 36353539, 2022). "Although BCL2 has elevated expression levels in many cancers and is an anticancer target, overexpression of BCL2 alone in cells does not impart tumorigenic potential but rather can have prosurvival benefits." (PMID 34949722, 2022). "By affecting the palmitoylation of GNA13, these cancer cells with a wild-type GNA13 protein became again sensitized to a BCL2 inhibitor, suggesting GNA13 palmitoylation as potential target for combinatory therapy with BCL2 inhibitors." (PMID 36226054, 2022). "Patients with Bcl-2 positive tumors have a better prognosis than those with Bcl-2 negative cancers, suggesting an unexpected link between an apoptotic inhibitor and a favorable result." (PMID 35887080, 2022). "This induction affects the ratio of BCL-2 to BAX, which may result in an alteration of apoptotic impulses and cancer cells’ resistance to therapeutic drugs." (PMID 35328794, 2022). "PROTAC 21 possessed a unique mechanism of action (MOA) in inhibiting antiapoptotic BCL-2 proteins, i.e. potent degradation of BCL-XL and simultaneously enhanced inhibition of BCL-2, that enabled its high potency against BCL-XL dependent, BCL-2 dependent, and BCL-XL/BCL-2 dual-dependent cancer cells." (PMID 35702041, 2022). "Our patient's cancer did have an MYC rearrangement but not BCL2 or BCL6 rearrangements, and cells displayed both mature and immature markers, making HGBL, NOS a possible diagnosis." (PMID 36158446, 2022). "Assessing the interaction of BCL-2 family proteins using immunoprecipitation upon exposure of ALL cells to BH3-mimetics, we observed decreased binding of BIM to BCL-2 upon exposure to venetoclax, but compensational increased binding to MCL-1 in other cancer cell types." (PMID 35031695, 2022).
cancer (continued). "As observed in the study, 7‐Epitaxol increases the expressions of pro‐apoptotic proteins Bid and Bim L/S and reduces the expressions of anti‐apoptotic proteins Bcl‐2 and Bcl‐XL, leading to activation of PARP and caspases 3, 8 and 9 and subsequent induction of cancer cell apoptosis." (PMID 36308422, 2022). "In contrast to typical BH3-only proteins that bind to anti-apoptotic Bcl-2 family proteins via their BH3 domain, BNIP3 interacts with Bcl-2 and Bcl-XL specifically through its TM domain and N-terminus in cancer and non-cancer somatic cells." (PMID 36402748, 2022). "We identified an enrichment for BCL2 in immune, and BAK, SMAC, and XIAP in cancer cells." (PMID 34754079, 2022). "ABT-199 efficiently stimulates cell death in Bcl-2-dependent cancers without inducing thrombocytopenia." (PMID 34638779, 2021). "Besides the anti-apoptotic function, BCL-2 and BCL-xL are emerged as master regulators of ER and mitochondrial dynamics in cancer cells." (PMID 34064109, 2021). "In addition, cancer cells from primary tumors release IL4, increasing the expression of anti-apoptotic proteins, such as cFLIP, Bcl-XL, and Bcl-2." (PMID 34371753, 2021). "BCL2, VEGFA and IL-6 were found to be enriched in pathways in cancer." (PMID 33510225, 2021). "Since BCL-2 and MCL-1 proteins may have overlapping anti-apoptotic functions with BCL-XL in cancer cells, we compared the impact of their mRNA expression levels, either alone or in combination with CDK1, CDK6 and WEE1, on the overall survival of TNBC patients." (PMID 34646365, 2021). "In line with anti-cancer effects, SSE attenuated apoptosis resistance in VSMCs, as evidenced by growth in the number of TUNEL positive cells and the expression of pro-apoptosis markers Bax/Bcl-2 and Cleaved Caspase-3." (PMID 33790787, 2021). "Previously reported meta-analysis suggested that BAX -248 G>A and BCL2 -938 C>A are not directly associated with the overall cancer susceptibility but the correlation could be ethnicity-specific, which probably contributes to increasing adverse prognosis of cancer." (PMID 33906310, 2021). "Moreover, we found that the combination of low-dose BGB-3111 with low-dose BTZ significantly enhanced the anti-cancer effects by increasing the expression of cleaved PARP and caspase-9 and inhibiting Bcl-2 expression and further affecting the NF-κB pathway." (PMID 34508613, 2021). "Because SS is known to overexpress BCL-2 and venetoclax-based combination therapies are very effective across multiple hematological cancers, we chose to focus on deciphering the role of BCL-2 family members in this cancer." (PMID 34065859, 2021). "Perhaps not surprisingly, the combination of CTR-21 and ABT-737, a Bcl-2 inhibitor, showed synergistic effect in killing cancer cells, since we previously found the “parental” CTR-20 also exhibited synergism." (PMID 34732782, 2021). "Furthermore, the KEGG pathway enrichment analysis of tRF-1:28-Val-CAC-2 was enriched in pathways in cancer, which included the Hedgehog signaling pathway with EVI1, BCL2, and PKA and the Wnt signaling pathway (not in the top 10) with Frizzled, Daam1, and NFAT." (PMID 34988117, 2021). "In studies conducted with TRAIL, it has been observed that Bcl-2 protein is generally overexpressed due to the non-effective dose of anti-cancer agent and thus improves resistance to apoptosis." (PMID 34567145, 2021). "Although more extensive tolerability data are still pending, this assumption is also supported by several successfully completed phase I/II clinical trials in various types of cancers with AT-101, a small molecule simultaneously targeting MCL1, BCL2 and BCL-xL." (PMID 34564697, 2021). "The BH3 domain of Bcl-2 protein interacts with pro-apoptotic proteins (e.g., Bim) and imposes inhibitory effect on apoptosis, whereas its BH4 domain interacts with IP3R isoforms, thus prevents Ca2+ flux into mitochondria and promotes cancer cell survival." (PMID 33599798, 2021).